IL1B (interleukin 1 beta)
Diseases named in the same sentence as IL1B in open-access papers (continued):
Sharing a sentence is not in itself a finding about the gene and the disease.
Cerebral ischemia (continued). "In the context of cerebral ischemia, TIGAR has been shown to exert neuroprotective effects by reducing oxidative stress, supporting mitochondrial function, and mediating downregulation of pro-inflammatory markers such as iNOS, COX-2, IL-1β, and TNF-α in astrocytes." (PMID 41342963, 2025). "In models of cerebral ischemia and neuronal cultures, EGCG promotes neuronal protection regulated by the Nrf2/HO-1 pathway by attenuating both ROS production and nuclear factor κB (NF-κB) activation, which consequently suppresses the expression of TNFα, IL-1β, IL-6, and iNOS." (PMID 32466215, 2020). "Moreover, Tat-NTS—a related peptide—protects against cerebral ischemia/reperfusion injury by enhancing SUMOylation of ANXA1, thereby promoting NBR1-dependent selective autophagic degradation of IKKα, suppressing NF-κB activation, and reducing IL-1β and TNF-α release in microglia." (PMID 41007413, 2025). "By replicating the rat model of cerebral ischemia, this study explored whether THSWD can reduce cell necrosis and neuroinflammation in the rat model of MCAO by inhibiting the expression levels of MCP-1, IL-1β, IBA-1, and MPO inflammatory factors as well as the TNF-α/RIP1/RIP3/MLKL pathway." (PMID 34447315, 2021). "It is notable that cerebral ischemia did not change the levels of plasma proinflammatory cytokines TNF-α and IL-1β, but significantly increased the levels of plasma IL-6 and C-reactive protein, which were attenuated by propofol treatment." (PMID 24349350, 2013). "The productions of IL-1β, TNF-α, PGE2, and NO significantly increased in rat cortex with cerebral ischemia." (PMID 23762140, 2013). "Indeed, the present study showed that PC(16:0/16:0) suppressed LPS-evoked microglial production of IL-1β and TNF-α, while LPC(16:0) did not, indicating that cerebral ischemia tipped the balance of PC-LPC ratio, which is regulated by the Lands cycle." (PMID 33288676, 2021).
endothelial dysfunction (230 papers, 2009 to 2026). In vascular diseases, endothelial dysfunction is a systemic pathological state of the endothelium (the inner lining of blood vessels) and can be broadly defined as an imbalance between vasodilating and vasoconstricting substances produced by (or acting on) the endothelium. "Pollutants like Particulate matter smaller than 2.5 microns can cause the body to produce interleukins (IL-6, IL-1β), which can contribute to endothelial dysfunction, a common sign of preeclampsia." (PMID 41289532, 2025). "Stronger evidence supports the role of periodontal inflammation and oral microbiota dysbiosis in systemic inflammatory burden, with elevated mediators such as CRP, IL-6, TNF-α, and IL-1β implicated in endothelial dysfunction and atherogenesis." (PMID 41294894, 2025). "Tumor-secreted pro-inflammatory cytokines, such as IL-1β and IL-6, exacerbate endothelial dysfunction and vascular inflammation, further predisposing patients to CVD." (PMID 40227756, 2025). "Cytokines such as interleukin (IL)-6, tumor necrosis factor-alpha (TNF-α), and IL-1β have been implicated in the inflammatory cascade, leading to endothelial dysfunction and myocardial stress, thereby increasing the susceptibility to arrhythmias." (PMID 40151738, 2025). "When patients were stratified according to the degree of stenosis, serum from HGS patients induced more pronounced carotid artery endothelial dysfunction, an effect that was associated with enhanced circulating levels of IL-1β." (PMID 36536168, 2024). "It is known that IL-1 is a possible mediator of maternal endothelial dysfunction in preeclampsia, and aberrant IL-1β levels were shown to be associated with a variety of gestational diseases, such as preeclampsia, preterm labor, and spontaneous abortion." (PMID 36355514, 2022). "Our study showed that a higher level of ADMA is associated with a higher level of MMP-9 and IL-1β, indicating inflammation and endothelial dysfunction can promote stenosis dysfunction of VA and lead to shorter duration of VA use." (PMID 33917703, 2021). "The effect of IL-1β on endothelial dysfunction was prevented by co-treatment with SB suggesting that IL-1β signals via a p38MAPK-associated pathway to impair endothelial function." (PMID 31412063, 2019). "IL-1β has also been implicated in promoting angiogenesis and blocking IL-1 improved endothelial dysfunction in streptozotocin-induced diabetic rats and prevented choroidal neovascularization in laser-induced retinal degeneration models." (PMID 26514658, 2015). "Additional assessments for evaluating endothelial dysfunction involve measuring biomarkers in the blood that indicate harmful events in the heart and vessels, like the release of cytokines linked to inflammation (IL‐6 and IL‐1β)." (PMID 39040847, 2024). "NLRP3 activation and ER stress induces placental release of pregnancy-incompatible factors including sFlt-1, IL1β, and other pro-inflammatory cytokines and alarmins into maternal circulation causing oxidative stress, systemic inflammation, and endothelial dysfunction." (PMID 37292200, 2023). "In addition to directly causing endothelial dysfunction by increasing vascular permeability, IL-1β promotes the proliferative activity in SMCs, causing intimal occlusion and compensatory collateral formation." (PMID 33567654, 2021). "The increase in SREBP-1 activity and IL-1β production in lesions is associated with vascular inflammation and endothelial dysfunction in atherosclerotic pig aorta, as demonstrated by the induction of NF-κB, VCAM-1, iNOS, and COX-2, as well as by the repression of eNOS." (PMID 23825667, 2013). "Additionally, the IL-1β and sST2 may exacerbate systemic inflammation by promoting macrophage activation and endothelial dysfunction, thereby increasing the risk of thrombosis and cardiovascular complications." (PMID 40710798, 2025).
endothelial dysfunction (continued). "Moreover, ROS are also responsible for pathological processes in the vasculature, causing endothelial dysfunction through the interruption of vasoprotective pathways such as NO signaling, as well as triggering inflammasome and cytokines such as IL-1β and IL-8 via activation of caspase-1." (PMID 36839268, 2023). "Its mechanism of action involves preventing the oligomerization of the inflammasome complex, leading to decreased expression of inflammatory cytokines (such as IL-1β and IL-18), as well as reduced renal fibrosis, endothelial dysfunction, and oxidative stress." (PMID 40867825, 2025). "IL-1β and IL-6 are key drivers of endothelial dysfunction and plaque destabilization, while TNF-α is involved in amplifying the inflammatory cascade and enhancing cellular adhesion, making them particularly relevant therapeutic targets." (PMID 40727466, 2025). "Pro-inflammatory agents like tumor necrosis factor-α (TNF-α), interleukin-6 (IL-6), interleukin-1β (IL-1β), and vascular endothelial growth factors can further exacerbate vascular injury and endothelial dysfunction, leading to vascular remodeling." (PMID 40933377, 2025). "Influenza infection triggers a surge in cytokines like IL-1β, IL-6, and TNFα, which contribute to endothelial dysfunction, increased monocyte recruitment, and macrophage infiltration into plaques, making them more prone to rupture." (PMID 41439053, 2025). "IL-1β is involved in various stages of atherosclerotic plaque formation, including endothelial dysfunction, immune cell recruitment, and lipid metabolism." (PMID 40728694, 2025). "The inflammatory response leads to the release of pro-inflammatory cytokines such as TNF-α, IL-6, and IL-1β, which contribute to endothelial dysfunction and reduced nitric oxide (NO) production, ultimately exacerbating ED development." (PMID 40529500, 2025). "IL-1β acts as a central inflammatory mediator, promoting endothelial dysfunction and smooth muscle proliferation." (PMID 40217801, 2025). "The inflammatory response triggered by pneumonia involves a cascade of cytokines, including IL-6, TNF-α, and IL-1β, which contribute to endothelial dysfunction and myocardial stress." (PMID 40151738, 2025). "These cascades result in increased transcription of pro-inflammatory cytokines (e.g., TNF-α, IL-6, IL-1β), endothelial dysfunction, and leukocyte recruitment, which together exacerbate tissue inflammation and injury." (PMID 40926894, 2025). "QPCR assays showed that the mRNA levels of inflammatory cytokines (IL-1β) and adhesion molecules (ICAM-1 and MCP-1) associated with endothelial dysfunction were elevated to varying degrees in OGD/OGR treated cells while SCU reversed these phenomena." (PMID 40098620, 2025). "These foam cells release cytokines such as tumor necrosis factor-α (TNF-α) and interleukin-1β (IL-1β), exacerbating endothelial dysfunction and sustaining local inflammation." (PMID 41347045, 2025). "During inflammation, levels of proinflammatory cytokines such as tumor necrosis factor (TNF)-α, interleukin (IL)-6, and IL-1β increase, which trigger apoptosis and fibrosis in cardiomyocytes and contribute to endothelial dysfunction, are increased." (PMID 40004844, 2025). "Elevated levels of circulating pro-inflammatory cytokines, such as IL-6, TNF-α, and IL-1β, create a sustained inflammatory milieu that exacerbates vascular oxidative stress and accelerates endothelial dysfunction." (PMID 40113668, 2025). "First, cytokines such as IL-6, TNF-α, and IL-1β, which are typically elevated in malignancy, promote endothelial dysfunction, upregulate adhesion molecules, and activate platelets." (PMID 41583284, 2025). "Activation of the NLRP3 inflammasome promotes the maturation and release of IL-1β and IL-18, contributing to endothelial dysfunction, macrophage pyroptosis, and plaque progression." (PMID 40871049, 2025).
endothelial dysfunction (continued). "Activation of NLRP3 in the placenta, uterus, kidneys, and maternal endothelium leads to the production of pro-inflammatory cytokines (IL-1β and IL-18) and triggers processes such as endothelial dysfunction, sodium retention, and hypertension." (PMID 40867825, 2025). "Compared with static control, d-flow upregulates pro-inflammatory cytokines (e.g., TNF- tumor necrosis factor and IL-1β), cell death pathway, and the senescence pathway; all contribute to endothelial dysfunction." (PMID 38646649, 2024). "Activation of NF-κB and NLRP3 inflammasome is associated with production of tumor necrosis factor-alpha (TNF-α), IL-1β, and IL-6 inflammatory cytokines leading to vascular damage, endothelial dysfunction resulting in hypertension and cardiovascular disease." (PMID 39081863, 2024). "Nishimatsu found that injection of the pro-inflammatory cytokine-, TNF-α-, and IL-1β-producing senescent cells in mice can impair erectile response by triggering endothelial dysfunction and nerve damage." (PMID 39022340, 2024). "Proinflammatory cytokines, including tumor necrosis factor-alpha (TNF-α), interleukin-1 beta (IL-1β), and IL-6, are elevated in this context, contributing to vascular inflammation and endothelial dysfunction." (PMID 39497887, 2024). "IL-4 and IL-13 are associated with cardiac fibrosis and hypertrophy, while IL-1β mediates inflammation, endothelial dysfunction and myocardial injury." (PMID 39633480, 2024). "Endothelial dysfunction is essential in the pathogenesis of AS, which releases inflammatory cytokines to VSMCs contributing to AS, including interleukin-1β (IL-1β), tumor necrosis factor-a (TNF-α), and transforming growth factor-β (TGF-β)." (PMID 37469665, 2023). "Upon leukocyte activation, endothelial dysfunction and other common pathogenic mechanisms, NLRP3 inflammasome activation, and IL-1β production are promoted in individuals with risk factors for CVDs." (PMID 37680887, 2023). "Elevated levels of IL-1β and TNF-α have been associated with endothelial dysfunction and contribute to the pathogenesis of IRI." (PMID 37675177, 2023). "Although we have not analysed the mechanisms by which TLR4 blockade improves the IL-1β-induced endothelial dysfunction, the reduction of oxidative stress might contribute to this effect, as has been reported in the hypertension-associated endothelial dysfunction." (PMID 36937865, 2023). "In summary, these results indicate a beneficial role for Nrf2 activation on vascular alterations such as VSMC migration and proliferation and the endothelial dysfunction induced by IL-1β." (PMID 36937865, 2023). "For example, it has been shown that IL-1β plays a role in endothelial dysfunction, abdominal aortic aneurysm formation, and atherosclerotic plaques in humans." (PMID 37581942, 2023). "TBHQ did not modify the vasodilator response induced by ACh, but it partially prevented the IL-1β-induced endothelial dysfunction." (PMID 36937865, 2023). "The Inflammatory response is tightly involved in sustaining the development of endothelial dysfunction, as has been proved by the detection of IL-1β (interleukin-1β) which is an important cytokine with inflammatory function." (PMID 36984870, 2023). "Endothelial dysfunction and local inflammation lead to activation of the endothelium via cytokines such as tumor necrosis factor or interleukin 1 beta." (PMID 37086290, 2023). "All these findings suggest a potential benefit of IL-1β-inhibitory therapies in the management of vascular aging, although further understanding of the mechanisms linking inflammation, IL-1β, endothelial dysfunction and cell senescence is needed." (PMID 35111374, 2022). "Mechanistically, a combination of mycolactone’s action at the Sec61 translocon, and increased local concentration of IL-1β likely explains the endothelial dysfunction seen in BU." (PMID 35100311, 2022).
endothelial dysfunction (continued). "In said context, PCSK9 deficiency reduces endothelial dysfunction by reducing the expression of lower endothelial expression of the genes encoding, e.g., ICAM-1, CCL2, IL-6 and IL-1β." (PMID 36361853, 2022). "The cytokines tumor necrosis factor alpha, interleukin-1 beta, and interleukin-6 have particular effects on endothelial cells—leading to endothelial dysfunction, endothelial cell death, changes in tight junctions, and vascular hyperpermeability." (PMID 35682871, 2022). "IL-1β is important in the inflammatory process that leads to endothelial dysfunction of blood vessels to develop hypertension." (PMID 35505381, 2022). "Further, IL1β is known to act as a potential mediator of endothelial dysfunction by inducing structural and functional alterations in endothelial cells, which is a hallmark of the maternal syndrome in PE." (PMID 35299960, 2022). "A key role in the formation of initial arteriosclerotic lesions is played by an inflammatory interleukin-1 beta (IL-1β), which induces endothelial dysfunction." (PMID 35889799, 2022). "The paracrine effects of PRAT inflammation, presented as higher IL-1β expression, lead to renovascular endothelial dysfunction, hyperfiltration, renal cortical inflammation and proteinuria." (PMID 34408726, 2021). "As a part of chronic inflammation, endothelial cells are continuously activated by inflammatory stimuli, including IL-6, TNF-α, and IL-1β, resulting in endothelial dysfunction and the progression of fibrosis." (PMID 34202668, 2021). "Given the known mechanistic connections of BET inhibitors to interleukin-1β (IL-1β) for modulating inflammatory phenotypes, an IL-1β–induced model of endothelial dysfunction was used to recapitulate PH features in vitro." (PMID 34669463, 2021). "When TNFα was added to HUVECs to induce endothelial dysfunction, IL-1b expression was significantly increased from control levels and decreased with doses of bisoprolol and metoprolol, but not carvedilol." (PMID 34362171, 2021). "The effects of TNFα and IL1β blocking antibodies as well as FAK inhibitor on CAR-T therapy-induced endothelial dysfunction need to be verified in vivo." (PMID 34093519, 2021). "Previous vascular functional studies confirmed that NLRP3 inflammasome plays a pivotal role in the regulation of endothelial dysfunction by activation of caspase-1, IL-1β, and IL-18 in metabolic disease models." (PMID 34326395, 2021). "Proinflammatory cytokines play a pivotal role in endothelial dysfunction and IL-1β and TNFα belong to the ones that have attracted the most attention because of their crucial involvement in CVD." (PMID 32923484, 2020). "Several cytokines including IL-1β and IL-18 have also been correlated with maternal endothelial dysfunction." (PMID 32093005, 2020). "It has been reported that in OSA, the expression of IL-1β increased and the NF-kB pathway was activated, along with endothelial dysfunction induced by hypoxia/normoxia, all of which are synergistic with the formation and development of OSA." (PMID 31915037, 2020). "Chronic treatment with Cmpd17b for eight weeks reduced the IL1β expression and reversed endothelial dysfunction, suggesting an anti-inflammatory effect of Cmpd17b that is independent of any changes to metabolic profile." (PMID 32085666, 2020). "Baicalein displayed anti-inflammatory effects by attenuating endothelial dysfunction and the inflammatory mediators, such as IL-33, IL-6, IL-1β, MMP-9, and IL-13, in radiation enteropathy." (PMID 31474856, 2019). "In agreement with our results, a HT sulfate metabolite recovered the IL-1β-induced downregulation of let-7 miRNA in preventing endothelial dysfunction." (PMID 31627295, 2019). "Of note, IL-1β and IFN-γ are major drivers of vascular inflammation and endothelial dysfunction, and have been both associated with increased vascular permeability and the onset of shock in severe dengue." (PMID 31068600, 2019).